MIRLET7A1 (microRNA let-7a-1)
Synonyms: hsa-let-7a-1; LET7A1; MIRNLET7A1; let-7a-1
Gene: MicroRNA gene on chromosome 9 (94,175,957 to 94,176,036, forward strand). Ensembl gene ENSG00000199165.
Pathways (Reactome):
Immune System: Regulation of PD-L1(CD274) translation
Signal Transduction: TGFBR3 expression
Gene Ontology:
Biological process: miRNA-mediated post-transcriptional gene silencing
Cellular component: RISC complex
Homologues: Orthologues: chimpanzee ptr-let-7a-1 (100% identical), rabbit MIRLET7A1 (100% identical), guinea pig MIRLET7A1 (99% identical), mouse Mirlet7a-1 (99% identical), rat Mirlet7a1 (99% identical), macaque MIRLET7A1 (96% identical), pig ssc-let-7a-2 (96% identical). Paralogues in human: MIRLET7F2 (90% identical), MIRLET7A3 (78% identical), MIRLET7D (75% identical), MIRLET7F1 (71% identical), MIRLET7C (70% identical), MIRLET7G (70% identical), MIR98 (69% identical), MIRLET7A2 (65% identical), MIRLET7E (64% identical), MIRLET7I (59% identical).
Diseases named in the same sentence as MIRLET7A1 in open-access papers:
MIRLET7A1 is named in the same sentence as 2 diseases in open-access papers, as found by Europe PMC text mining. Sharing a sentence is not in itself a finding about the gene and the disease. The quoted sentences say what the papers report.
emphysema (1 paper, 2024). "In the present study, we established that the Mirlet7 family members encoded by the Mirlet7b/Mirlet7c2 and Mirlet7a1/Mirlet7f1/Mirlet7d clusters are downregulated in T cells from lungs of emphysema patients and emphysematous mice that were exposed to CS or nCB." (PMID 38722677, 2024). "Here, we show that overall expression of the Mirlet7 clusters, Mirlet7b/Mirlet7c2 and Mirlet7a1/Mirlet7f1/Mirlet7d, are reduced in the lungs and T cells of smokers with emphysema as well as in mice with cigarette smoke (CS)- or nCB-elicited emphysema." (PMID 38722677, 2024). "Next, we elucidated Mirlet7b/Mirlet7c2 and Mirlet7a1/Mirlet7f1/Mirlet7d cluster expression (herein referred to as Mirlet7bc2 and Mirlet7afd, respectively) in murine models of CS- or nCB-induced emphysema, respectively." (PMID 38722677, 2024). "Paralleling our observations in human COPD and emphysema, mice with CS- or nCB-induced emphysema exhibited reduced expression levels of pri-Mirlet7b/c2 and pri-Mirlet7a1/f1/d transcripts in the lung and from isolated lung CD4+ and CD8+ T cells." (PMID 38722677, 2024). "Consistently, the analogous murine Mirlet7b/Mirlet7c2 and Mirlet7a1/Mirlet7f1/Mirlet7d clusters, respectively, were similarly downregulated in pre-clinical emphysema models." (PMID 38722677, 2024). "We did not ascertain whether deletion of Mirlet7a1/Mirlet7f1/Mirlet7d cluster is an equally or more effective modulator of experimentally induced emphysema." (PMID 38722677, 2024).
cancer (1 paper, 2018). A tumor composed of atypical neoplastic, often pleomorphic cells that invade other tissues. "MIRLET7A1, MIRLET7F1, MIRLET7D are microRNA genes which are involved in cancer and DNA damage response pathways." (PMID 30386687, 2018).